RNU6-295P (RNA, U6 small nuclear 295, pseudogene)
Gene: Small nuclear RNA gene on chromosome 8 (48,307,927 to 48,308,030, reverse strand). Ensembl gene ENSG00000252710.
Homologues: Orthologues: chimpanzee U6 (100% identical), macaque U6 (93% identical), guinea pig U6 (81% identical), pig U6 (81% identical), mouse Gm24537 (69% identical). Paralogues in human: RNU6-24P (85% identical), RNU6-28P (85% identical), RNU6-34P (85% identical), RNU6-726P (85% identical), RNU6-842P (85% identical), RNU6-1060P (84% identical), RNU6-1083P (84% identical), RNU6-1117P (84% identical), RNU6-112P (84% identical), RNU6-11P (84% identical), RNU6-140P (84% identical), RNU6-242P (84% identical), and 1284 more.